LTB4R (leukotriene B4 receptor)
Diseases named in the same sentence as LTB4R in open-access papers (continued):
Sharing a sentence is not in itself a finding about the gene and the disease.
ulcerative colitis (1 paper, 2022). An inflammatory bowel disease involving the mucosal surface of the large intestine and rectum. "Since many mucosal inflammatory diseases such as IBD are associated with mucosal wounds, we examined expression of LTB4R mRNA in tissue sections from samples from individuals with IBD (active ulcerative colitis)." (PMID 36301666, 2022).
tumor (31 papers, 2008 to 2026). "By integrating and analysing the multi-omics data and clinical data from tumour tissues and peripheral blood, we confirmed that the LTB4R gene is significantly upregulated not only in tumour tissues but also in the peripheral blood of CRC patients." (PMID 41898436, 2026). "LTB4R coordinates eicosanoid-mediated leukocyte trafficking and T-cell infiltration, potentially shaping tumor immune landscapes under PD-1 therapy." (PMID 41601673, 2026). "Correspondingly, in vivo tests indicated that LTB4R knockdown led to markedly slower tumor growth in mice models." (PMID 38259082, 2024). "LTB4, a leukotriene early mediator of inflammation, produced by mast cells of silica exposed lungs, is able to recruit neutrophils by interacting with BLT1, a leukotriene B4 receptor, on neutrophils and stimulates rapid tumor growth." (PMID 31799175, 2019). "Moreover, in an in vivo setting, mice with LTB4R knockdown tumors exhibited noticeably slower tumor growth compared to their control counterparts." (PMID 38259082, 2024). "Indeed, cisplatin increased oxPAPC level in tumour tissues of WT mice, CCL2−/− and LTB4R−/− mice, but caused increased infiltration of Ly6Chigh monocytes and neutrophils only in WT LL2‐bearing mice." (PMID 37905494, 2024). "Upregulation of LTB4R/LTB4R2 in a subset of TNBC samples suggests that the expression levels of these receptors may be employed in the future as a marker of tumor sensitivity to leukotriene receptor inhibitors." (PMID 38139172, 2023). "Moreover, the results also suggested that high expression of GNRH1 (F = 2.63, P = 0.0497) and LTB4R (F = 3.16, P = 0.0243) were significantly related to higher tumor stage." (PMID 34229684, 2021). "LTB4R is a potent lipid mediator that regulates allergy, inflammation, and immune responses, and has been shown to be upregulated in a variety of tumors and to play a potential role in the early stages of tumor development." (PMID 33968297, 2021). "We established LL2 tumour‐bearing models in WT, CCL2−/− and LTB4R−/− mice, and treated them with oxPAPC." (PMID 37905494, 2024). "At last, we confirmed that cisplatin induces oxPAPC release, and thus promotes MDSCs infiltration to tumour via activating the MCP‐1/CCL2 and LTB4/LTB4R axis, potentially boosting tumour growth." (PMID 37905494, 2024). "To address this critical question, we constructed LL2 subcutaneous tumour models of WT, CCL2−/−, and LTB4R−/− mice and treated them with oxPAPC on day 0 after tumour inoculation (10 mg/kg, intraperitoneal injection, once every other day)." (PMID 37905494, 2024). "Consistent with this, our in vivo experiments proved that oxPAPC triggered macrophages secreting MCP‐1 and LTB‐4, which recruited monocytes and neutrophils into tumour respectively through the MCP‐1/CCL2 and LTB‐4/LTB4R axis." (PMID 37905494, 2024). "Our findings conclusively showed that the increased infiltration of Ly6Chigh monocytes and neutrophils into tumour tissues elicited by oxPAPC treatment in vivo is mediated by MCP‐1/CCL2 and LTB4/LTB4R signalling pathways." (PMID 37905494, 2024). "In order to better simulate the effect and mechanism of the Ly6Chigh monocytes and neutrophils infiltration induced by cisplatin in vivo, we established LL2 tumour‐bearing model in WT mice, CCL2−/− mice and LTB4R−/− mice, and treated them with cisplatin." (PMID 37905494, 2024). "ANGPTL4, LTB4R, CD72, and NUDT6 were downregulated, as their expression levels were higher in the healthy group and lower in the tumor group." (PMID 36911403, 2023). "This analysis identified three genes expressed in tumor cells, i.e. ALOX15B, the leukotriene B4 receptor gene LTB4R2 and the PGE2 receptor gene PTGER3." (PMID 27215396, 2016). "Then the mRNA expression of prognostic biomarkers between tumor tissues and normal tissues was compared, the results indicated that both the genes including GNRH1 (P < 0.05), and LTB4R (P < 0.05) were significantly higher expressed in ccRCC samples compared to normal samples." (PMID 34229684, 2021).
tumor (continued). "Collectively, our work demonstrates cisplatin treatment induces an overproduction of oxPAPC and thus recruits MDSCs infiltration to promote the tumour growth through the MCP‐1/CCL2 and LTB4/LTB4R pathways, which may restrict the effect of multiple chemotherapy." (PMID 37905494, 2024). "Injection of oxPAPC in vivo significantly upregulated the percentage of MDSCs in tumour microenvironment (TME) of wild‐type LL2 tumour‐bearing mice, but not CCL2−/− mice and LTB4R−/− mice." (PMID 37905494, 2024). "As we expected, the flow cytometric results showed that Ly6Chigh monocytes and neutrophils markedly infiltrated in tumour tissues of oxPAPC‐treated WT mice, while there was no significant change in oxPAPC‐treated CCL2−/− mouse or LTB4R−/− mice compared with that in their respective control mice." (PMID 37905494, 2024).
cancer (27 papers, 2008 to 2025). A tumor composed of atypical neoplastic, often pleomorphic cells that invade other tissues. "Leukotriene B4 Receptor 1 (LTB4R), a novel immune-related gene associated in our previous research with the prognosis of ccRCC patients, has been found in many cancers; however, its potential mechanism in renal clear carcinoma is unclear." (PMID 36429034, 2022). "Recent studies underscore the centrality of LTB4R in cancer research, owing to its multifarious roles." (PMID 38259082, 2024). "CYSLTR1 and PTGER4 are primarily expressed by immune cells in human cancers, while LTB4R, PTGER1 and PTGER3 are found in neuroendocrine and tuft cells." (PMID 37386128, 2023). "IRS of LTB4R was medium in cancer tissue and basal stratum of esophageal epithelium in cancer patients, whereas in control epithelium basal cells presented a weak reactivity." (PMID 27475906, 2016). "The increase of LTB4R mRNA in normal mucosa of patients with cancer compared to control was statistically significant (p < 0.05)." (PMID 27475906, 2016). "Considering the importance of the PI3K signaling pathway in cellular survival, growth, and proliferation, especially in the context of cancer progression, we sought to elucidate the potential interplay between LTB4R expression and this critical pathway in CRC cells." (PMID 38259082, 2024). "High expression LTB4R has been reported in various cancers, including PCa." (PMID 36497496, 2022). "The LTB4R mRNA showed an increase of the transcript in cancer tissue (1.69-fold) and non-transformed esophageal epithelium of cancer patients (2.24-fold) compared to control." (PMID 27475906, 2016). "We have hypothesized that the expression and/or DNA methylation of LTB4R/LTB4R2 genes might be promising prognostic and predictive markers useful in developing individualized therapy with leukotriene receptor inhibitors for malignant tumors, including BC." (PMID 38139172, 2023). "Interestingly, an increased expression of LTB4R was observed also in non-transformed esophageal mucosa of cancer patients compared to control." (PMID 27475906, 2016).
infection (17 papers, 2012 to 2025). The state of being infected such as from the introduction of a foreign agent such as serum, vaccine, antigenic substance or organism. "For instance, deletion of the leukotriene B4 receptor (LTB4R) in mice results in a deficiency in neutrophil and eosinophil recruitment and increased susceptibility to infection." (PMID 37435068, 2023). "Neutrophil swarm function required leukotriene B4 receptor 1 (BLT1) expression, and swarms were further characterized by peripheral association of polymorphonuclear myeloid-derived suppressor cells (PMN-MDSCs) showing that OPC recruits PMN-MDSCs to this site of infection." (PMID 37886517, 2023).
inflammation (2 papers, 2021 to 2023). Aberrant reaction of the microcirculation characterized by movement of fluid and leukocytes from the blood into extravascular tissues. "In murine studies, blocking LTB4R led to the inhibition of both early-phases and late-phases of allergen-induced airway inflammation." (PMID 38057814, 2023).
skin disorder (1 paper, 2023). Any deviation from the normal structure or function of the skin or subcutaneous tissue that is manifested by a characteristic set of symptoms and signs. "Similarly, other genes linked to skin disorders include PSORS1C3 (spring-born), and LTB4R (winter-born), both of which are known to be linked to the autoimmune disease psoriasis." (PMID 37697338, 2023).
LTB4R also shares sentences with these, for which no sentence is quoted: colon carcinoma (6 papers); rheumatoid arthritis (5); COVID-19 (3); inflammatory bowel disease (3); multiple sclerosis (3); myocardial infarction (3); airway hyperresponsiveness (2); allergic dermatitis (2); Allergy (2); autoimmune disease (2); colorectal cancer (2); experimental autoimmune encephalomyelitis (2); Glucose intolerance (2); influenza (2); intracerebral hemorrhage (2); ischemic stroke (2); leukemia (2); melanoma (2); metabolic disease (2); peritonitis (2); skin inflammation (2); Stroke (2); Ureteral obstruction (2); abdominal aortic aneurysm (1); abscess (1); acute myocardial infarction (1); acute pancreatitis (1); age-related macular degeneration (1); allergic conjunctivitis (1); allergic contact dermatitis (1).
A further 54 diseases each share a sentence with LTB4R in 1 paper.